LOX (lysyl oxidase)
Diseases named in the same sentence as LOX in open-access papers (continued):
Sharing a sentence is not in itself a finding about the gene and the disease.
bladder cancer (5 papers, 2010 to 2025). "The association between Hpa2 and LOX levels was further confirmed clinically, because the majority of bladder carcinomas that exhibited strong staining of Hpa2 also showed strong staining of LOX." (PMID 26968815, 2016). "Clearly, more work is required to resolve the role of LOX and LOX-related enzymes in bladder cancer." (PMID 26968815, 2016). "In order to further reveal the clinical significance of LOX in bladder cancer we next subjected the bladder tissue array to immunostaining applying anti-LOX antibody." (PMID 26968815, 2016). "Interestingly, the TM4SF1, ANXA1 and LOX genes have been identified in a fibroblast cluster for good prognosis in bladder cancer and are seen as therapeutic targets for fibrosis." (PMID 40271554, 2025). "Indeed, we found that Hpa2 is involved in the regulation of gene expression, best exemplified by enhanced LOX and E-cadherin expression in 5637 bladder carcinoma cells over expressing Hpa2." (PMID 26968815, 2016). "LOX and LOXL2 reportedly promote kidney carcinoma tumorigenesis, while LOX, LOXL1 and LOXL4 suppress bladder cancer growth." (PMID 29732010, 2018). "The role of LOX in bladder cancer has not been so far resolved." (PMID 26968815, 2016).
cardiac hypertrophy (5 papers, 2019 to 2023). "Since TGF-β isoforms are key mediators of fibrosis and cardiac hypertrophy across many species and upregulated by lumican and LOX in vitro, we explored their potential role in myocardial remodelling in feline HCM." (PMID 37443910, 2023). "More interestingly, LOX transgenesis exacerbated the cardiac hypertrophy and dysfunction induced by the chronic infusion of Angiotensin II (Ang II), triggering a more severe fibrotic process with higher collagen deposition and CCL and an enhanced expression of fibrotic markers." (PMID 31766500, 2019). "Transgenic overexpression of LOX or LOXL1 aggravated cardiac hypertrophy in mice with or without angiotensin II induction." (PMID 36159334, 2022). "LOX inhibition by BAPN significantly attenuated these changes and improved cardiac hypertrophy." (PMID 31766500, 2019).
Cirrhosis (5 papers, 2018 to 2024). A chronic disorder of the liver in which liver tissue becomes scarred and is partially replaced by regenerative nodules and fibrotic tissue resulting in loss of liver function. "In a carbon tetrachloride (CCl4) model of murine cirrhosis, it was found that myofibroblastic differentiation preceded excessive ECM deposition and was related to increased stiffness due to LOX (lysyl oxidase)-mediated cross-linking of already present collagen fibres." (PMID 37841641, 2023).
Ewing sarcoma (5 papers, 2013 to 2025). A small round cell tumor that lacks morphologic, immunohistochemical, and electron microscopic evidence of neuroectodermal differentiation. "In agreement with this, LOX expression was found to be low or undetectable in a group of Ewing sarcoma cell lines and primary tumors." (PMID 26258070, 2015). "The mechanisms involved in LOX-PP-mediated suppression in Ewing sarcoma have only been partially studied." (PMID 26258070, 2015). "Ectopic expression of LOX propeptide in an Ewing sarcoma cell line reduced cell proliferation, cell migration, anchorage independent growth and tumor growth in vivo." (PMID 23750284, 2013). "Time-course experiments confirmed that LOX is a gene downregulated by EWS/FLI1, since LOX mRNA levels were significantly upregulated upon EWS/FLI1 knockdown in the A673 Ewing sarcoma cell line." (PMID 23750284, 2013). "Microarray studies and real time quantitative RT-PCR demonstrated that LOX mRNA was downregulated by the EWS/FLI1 oncoprotein in the A673 Ewing sarcoma cell line." (PMID 23750284, 2013). "One of the most interesting findings of our work is the demonstration that lysyl oxidase and particularly, the lysyl oxidase propeptide (LOX-PP) is a suppressor of Ewing sarcoma tumorigenesis." (PMID 23750284, 2013). "Analysis of our gene expression profile dataset in the Ewing sarcoma cell line A673 upon EWS/FLI1 knockdown showed that one of the most strongly downregulated genes by EWS/FLI1 codes for the enzyme lysyl oxidase (LOX)." (PMID 23750284, 2013). "In this work, we show that EWS/FLI1 downregulates LOX expression and that, remarkably, LOX propeptide exhibits tumor suppressor activities in Ewing tumor cells." (PMID 23750284, 2013). "In summary, our observations indicate that deregulation of the LOX gene participates in Ewing sarcoma development and identify LOX-PP as a new therapeutic target for one of the most aggressive paediatric malignancies." (PMID 23750284, 2013). "Our data indicates that LOX propeptide is a tumor suppressor gene in Ewing's tumors, providing the bases for a rational use of LOX propeptide, derived peptides or synthetic peptidomimetics in Ewing's therapy." (PMID 23750284, 2013). "Using a doxycycline inducible system to restore LOX expression in an Ewing sarcoma derived cell line, we showed that LOX displays tumor suppressor activities." (PMID 23750284, 2013). "Next, expression levels of eight EWS-FLI1 associated target genes (GLI1, NEX2.2, CyclinD, c-MYC, NR01B, IGF1R, EZH2, and CD99) which were known to be upregulated, and three genes (FOXO1, IGFBP3, and LOX) known to be down regulated in Ewing’s sarcoma was assessed." (PMID 28775288, 2017). "Recently, a connection between LOX and Ewing sarcoma pathogenesis has been also demonstrated." (PMID 26258070, 2015). "Since these data suggested that LOX could act as a tumor suppressor in Ewing sarcoma, functional studies were carried out." (PMID 26258070, 2015). "Thus, EWS/FLI1 knockdown in Ewing sarcoma cells induces the expression of LOX indicating that this gene is strongly repressed by EWS/FLI1 in these cells." (PMID 26258070, 2015). "Interestingly, when full-length LOX protein (preLOX) was expressed in Ewing tumor cells, the inhibitory effect of LOX-PP on cell proliferation was dominant on the stimulatory effect mediated by LOXenz." (PMID 23750284, 2013). "Although in that study it was not analysed the effect of LOX propeptide itself, these results, taken together with ours, suggest that LOX-PP could act as an antitumor agent for the majority of Ewing sarcoma cells." (PMID 23750284, 2013). "The fact that EWS/FLI1 downregulates LOX in the A673 Ewing sarcoma cell line and that low levels of LOX are a common feature of Ewing sarcoma cells and tumors, suggest that LOX could act as a tumor suppressor in Ewing tumors." (PMID 23750284, 2013).
Ewing sarcoma (continued). "Next, we analysed if epigenetic mechanisms, known to repress gene expression, could be involved in the negative regulation of LOX expression observed in Ewing sarcoma cells." (PMID 23750284, 2013). "Thus, preLOX expression produced a net inhibitory effect on cell proliferation, which could explain why LOX downregulation is advantageous for Ewing tumor cells." (PMID 23750284, 2013). "A recent study used LOX as a surrogate marker of low EWS-FLI1 expression and identified such cells to be present at an incidence of 2% in primary Ewing sarcomas." (PMID 32326412, 2020). "Interestingly, the use of HDACs inhibitors (vorinostat/SAHA) or LSD1 inhibitors (HCI-2509) induced an increase in the levels of LOX mRNA in A673 Ewing sarcoma cells, which suggest that the anti-tumor effect of these drugs could be mediated, at least in part, by the upregulation of LOX." (PMID 26258070, 2015). "In this case, LOX re-expression should antagonize, at least in part, the transforming properties of EWS/FLI1 in Ewing tumor cells." (PMID 23750284, 2013). "It is therefore possible, although still hypothetical, that LOX-mediated shaping of ECM stiffness may affect YAP/TAZ signaling and metastasis in Ewing sarcoma with low EWS-FLI1 expression as well." (PMID 32326412, 2020). "LOX expression in these Ewing sarcoma cell lines was nearly undetectable, while high LOX expression was observed in IMR-90 normal fibroblasts, which were used here as a positive control of LOX expression." (PMID 23750284, 2013). "Currently, no data are available about the possible contribution of LOX repression to the malignant phenotype of Ewing sarcoma." (PMID 23750284, 2013). "While fluctuations in EWS-FLI1 levels and the ensuing consequences for YAP/TAZ signaling may be the basis for the metastatic potential of a small fraction of tumor cells in Ewing sarcoma (2% according to the postulated biomarker LOX), they may not fully explain Ewing sarcoma aggressiveness." (PMID 32326412, 2020). "In this study we show that lysyl oxidase (LOX), an enzyme involved in maintaining structural integrity of the extracellular matrix, is downregulated by the EWS/FLI1 oncoprotein and in consequence it is not expressed in Ewing sarcoma cells and primary tumors." (PMID 23750284, 2013).
Insulin resistance (5 papers, 2015 to 2024). Increased resistance towards insulin, that is, diminished effectiveness of insulin in reducing blood glucose levels. "More interestingly, we have observed that inhibition of LOX activity attenuates insulin resistance in obese animals." (PMID 26035864, 2015). "LOX is downregulated during adipocyte differentiation, and our data shows that inhibition of LOX impacts adipocyte homeostasis and improves insulin resistance in the well-established model of TNFα-induced insulin resistance." (PMID 26035864, 2015). "Inhibition of LOX activity in transgenic HIF-1α mice resulted in an improvement in the insulin sensitivity which highlights the critical role of LOX in HIF-1α mediated fibrosis and insulin resistance." (PMID 30622603, 2018).
oral cancer (5 papers, 2019 to 2023). "Data provide initial evidence for rs1800449 as an oral cancer susceptibility biomarker and point to opportunities to better understand the functional mechanism of LOX-PP cancer inhibitory activity." (PMID 37298359, 2023). "Combined with increased OSCC associated with the LOX polymorphism in humans, data point to an important role for LOX-PP in oral-tissue homeostasis with relevance to the incidence of oral cancer that must be further explored." (PMID 37298359, 2023). "In summary, our in silico and in vivo data indicate that the LOX-PP polymorphism results in increased incidence and severity of oral cancer development." (PMID 37298359, 2023). "The data suggest that there is a strong association between LOX-PP polymorphism and the development of oral cancer." (PMID 37298359, 2023). "To investigate this possibility, we treated cultures of the mouse oral-cancer cell line LY2 with recombinant wild with vehicle type rat Arg LOX-PP or Gln LOX-PP overnight in serum-free medium followed by a Western blot of three cultures each." (PMID 37298359, 2023). "The scratch test and the migration assay showed that the migratory ability of oral cancer cells was weakened upon LOX knockdown." (PMID 34930321, 2021). "In poorly differentiated oral cancer, LOX staining appeared to be mostly restricted to the epithelium that exhibited light counterstaining consistent with keratinocyte edema." (PMID 31086173, 2019). "In differentiated oral cancer, LOX and LOXL2 were clearly expressed in tumor nests, and in associated elongated cells with a mesenchymal morphology." (PMID 31086173, 2019). "By conducting the LY2 cell-culture model of oral cancer and treating cells with Arg LOX-PP or Gln LOX-PP recombinant protein, the more pro-LOX protein was observed to be expressed following Gln LOX-PP treatment, while less was expressed after wildtype Arg LOX-PP treatment." (PMID 37298359, 2023).
Osteopenia (5 papers, 2014 to 2021). Osteopenia is a term to define bone density that is not normal but also not as low as osteoporosis. "This has a relevance to inflammation-associated osteopenia, which is associated with a downregulation of LOX in response to tumor necrosis factor alpha (TNFα)." (PMID 25978957, 2015). "We propose that down-regulation of lysyl oxidase in pluripotent cells by TNF-α in inflammatory diseases can lead to a smaller pool of precursor cells ultimately leading to a diminished population of bone or cartilage producing cells, and consequent osteopenia." (PMID 24971753, 2014).
renal carcinoma (5 papers, 2017 to 2024). A carcinoma arising from the epithelium of the renal parenchyma or the renal pelvis. "The role of LOX enzymes in the cause of neoplastic diseases such as colorectal, skin, pancreatic and renal cancers has been confirmed.There are two human forms of 15-LO, named 15-LO-1 and 15-LO-2." (PMID 28496472, 2017). "In the recent years, the role of LOX enzymes in the origin of neoplastic diseases such as colorectal, skin, pancreatic and renal cancers has been confirmed." (PMID 28496472, 2017). "In addition, LOX hasbeen shown to enhance renal cancer cell migration and invasion." (PMID 39398183, 2024).
serous ovarian cancer (5 papers, 2020 to 2024). "The results indicated that the overexpression of LOX, LOXL1, LOXL2, LOXL3, and LOXL4 mRNA in serous ovarian carcinoma patients was related to unfavorable OS and PFS." (PMID 33058284, 2020).
brain tumor (4 papers, 2015 to 2021). "Modifying the collagen matrix through inhibition of the collagen crosslinking enzyme lysyl oxidase alters the tumor microenvironment and decreases angiogenesis and progression of brain tumors in vitro and in vivo." (PMID 29644003, 2018).
cholangiocarcinoma (4 papers, 2021 to 2024). A carcinoma that arises from the intrahepatic biliary tree (intrahepatic cholangiocarcinoma) or from the junction, or adjacent to the junction, of the right and left hepatic ducts (hilar cholangiocarcinoma). "Mice bearing orthotopic and spontaneously occurring intrahepatic cholangiocarcinoma tumors exhibited delayed tumor growth and improved survival following a combination of pan-LOX inhibition with chemotherapy." (PMID 39101793, 2024). "In the liver, hepatic stellate cell production of LOX increases the metabolic fitness of cholangiocarcinoma in vivo, as demonstrated by inhibition studies." (PMID 39766266, 2024). "Whilst for cholangiocarcinoma (EGI-1) and pancreatic adenocarcinoma models (KPC and mPDAC), LOX inhibition drastically decreases tumor stiffness, this effect is less marked in the breast adenocarcinoma model (MMTV-PyMT)." (PMID 34106045, 2021).
COVID-19 (4 papers, 2022 to 2024). A disease caused by infection with severe acute respiratory syndrome coronavirus 2. "Other COVID-19 studies reported severity-dependent downregulation of DHA-derived SPMs, together with a shift in the expression of LOX enzymes." (PMID 35888743, 2022).
esophageal squamous cell carcinoma (4 papers, 2018 to 2024). Esophageal squamous cell carcinoma (ESCC) is a type of esophageal carcinoma (EC) that can affect any part of the esophagus, but is usually located in the upper or middle third. "Silencing or inhibition of LOX has been reported to suppress the migration, invasion, and growth ability of esophageal squamous cell carcinoma by downregulating PIK3 harboring a PIK3CA mutation." (PMID 34202354, 2021). "Although the LOX region of LOXL2Δ13 is shortened and its deamination activity is partially reduced, LOXL2Δ13 is more strongly transforming in esophageal squamous cell carcinoma cells, compared to LOXL2WT, indicating that the cancer-promoting function of LOXL2Δ13 does not depend on LOX activity." (PMID 38810697, 2024).
Inguinal hernia (4 papers, 2015 to 2022). Protrusion of the contents of the abdominal cavity through the inguinal canal. "Taken together, our data suggest that loss-of-function LOX variants cause a wide spectrum of aortic and arterial aneurysmal disease, combined with connective tissue findings such as inguinal hernia, pneumothorax, varices, joint dislocations and splenic rupture." (PMID 34281165, 2021). "Furthermore, bladder diverticula, inguinal hernia, skin laxity, hyperelasticity, and occipital exostosis are caused by reduced LOX activity." (PMID 26347346, 2015). "Pathway analyses identify several genes with a strong link to collagen and/or elastin (ADAMTS6, ADAMTS16, ADAMTSL3, LOX, ELN) in the vicinity of associated loci for inguinal hernia, which substantiates an essential role of connective tissue morphology." (PMID 35680855, 2022). "Two types of enzymes have been investigated for their role in inguinal hernia development: matrix metalloproteinases (MMPs), which digest proteins of the extracellular matrix to maintain tissue homeostasis, and lysyl oxidase, which cross-links collagen and elastin." (PMID 29018803, 2017). "Their influences on hernia development are not fully understood, but an increased activity of MMPs could explain the altered collagen ratios seen in inguinal hernias, and a decreased activity of lysyl oxidase would affect the elastic and mechanical strength of connective tissue." (PMID 29018803, 2017).
ischemia (4 papers, 2016 to 2021). A hypoperfusion of the BLOOD through an organ or tissue caused by a PATHOLOGIC CONSTRICTION or obstruction of its BLOOD VESSELS, or an absence of BLOOD CIRCULATION. "The infarct size averaged 56.24 ± 9.44% in control-isolated hearts subjected to 35 min global ischemia followed by reperfusion, and was not modified in hearts from LOX-over-expressing mice." (PMID 35052579, 2021).
metabolic syndrome (4 papers, 2013 to 2019). A cluster of metabolic risk factors for CARDIOVASCULAR DISEASES and TYPE 2 DIABETES MELLITUS. "The LOX index is closely associated with recent smoking states as well as dyslipidemia and an inflammation marker." (PMID 28761986, 2018). "The LOX index is closely associated with smoking heaviness as well as dyslipidemia and an inflammation marker." (PMID 28761986, 2018). "Leptin induces LOX expression in cardiac myofibroblasts and vascular smooth muscle cells (VSMCs), and serum leptin levels have been found to correlate with cardiovascular disease risk and metabolic syndrome." (PMID 28036074, 2016). "An increase in myocardial LOX expression has also been reported in animal models of metabolic syndrome." (PMID 28036074, 2016).
oral submucous fibrosis (4 papers, 2018 to 2023). "The cDNA was prepared for 127 samples which were processed for gene expression of Lysyl oxidase (LOX) in relation to housekeeping genes (Beta actin and 18srRNA) and its role in pathogenesis of Oral submucous fibrosis." (PMID 31636853, 2019). "In oral submucous fibrosis, the expression of Lysyl oxidase gene is mixed type i.e either it will down regulate/up-regulate or there will be no expression at all comparatively." (PMID 31636853, 2019). "Identification and comparison of gene expression of Lysyl oxidase (LOX) in oral submucous fibrosis and controls and to determine its role in Pathogenesis of Oral submucous fibrosis." (PMID 31636853, 2019). "The increased level of soluble copper could act as an important factor in oral submucous fibrosis by stimulating fibrogenesis through upregulation of LOX activity." (PMID 31636853, 2019). "Key words:Oral submucous fibrosis, lysyl oxidase, betel nut, premalignant disorders." (PMID 31636853, 2019). "Although no reports have linked LOX genetic variance to cardiomyopathy, a single nucleotide polymorphism in the LOX coding region, G473A, which causes the non-conservative R158E mutation in LOX protein, is linked to oral submucous fibrosis." (PMID 35277059, 2022). "So the expression of lysyl oxidase gene can be used as adjunctive diagnostic tool for oral submucous fibrosis.As the expression of lysyl oxidase gene is mixed type in our study, we are not in agreement with previous studies that the lysyl oxidase gene is only upregulated." (PMID 31636853, 2019).